TRIM21 (tripartite motif containing 21)
Diseases named in the same sentence as TRIM21 in open-access papers (continued):
Sharing a sentence is not in itself a finding about the gene and the disease.
asthma (4 papers, 2019 to 2025). "In asthma, LncTRPM2-AS inhibits TRIM21 mediated TRPM2 ubiquitination and prevents macrophage autophagy induced apoptosis." (PMID 40170095, 2025). "Taken together, our findings demonstrate that lncTRPM2-AS blocks the ubiquitination of TRPM2 via TRIM21 and inhibits autophagy-induced apoptosis which may contribute to macrophage inflammation in asthma." (PMID 34903714, 2021). "Taken together, here we show for the first time that lncTRPM2-AS blocks TRIM21-dependent TRPM2 ubiquitination and thereby inhibits autophagy-induced apoptosis of macrophages in asthma." (PMID 34903714, 2021). "In summary, lncTRPM2-AS blocks TRIM21-dependent ubiquitination of TRPM2 and inhibits autophagy-induced apoptosis of macrophages in asthma." (PMID 34903714, 2021). "Human epithelial cells from patients with asthma stimulated in vitro with RV‐A16 showed an upregulation of genes involved in DNA‐sensing and STING pathway such as the DNA sensors ZBP1, IFI16 and the cytosolic TRIM21." (PMID 39466641, 2025).
bladder cancer (4 papers, 2019 to 2025). "The RNF26/TRIM21 complex is implicated in the proliferation and migration of bladder cancer cells via ZHX3." (PMID 40771930, 2025). "Multiple studies have shown that TRIM21 is associated with bladder cancer." (PMID 40723250, 2025). "Furthermore, RNF26 has been shown to interact with another E3 ligase, TRIM21, enhancing its K48-linked ubiquitination in bladder cancer cells." (PMID 40771930, 2025). "Meanwhile, the PTMA interacts with TRIM21 directly to regulate the Nrf2 expression through p62/Keap1 signaling in human bladder cancer." (PMID 30988666, 2019). "Another study revealed that TRIM21 is also associated with the interaction with ubiquitin-conjugating E2 enzyme (UBE2S) that leads to the ubiquitination of lipoma preferred partner (LPP) via K11-linked polyubiquitination, thereby promoting the lymphatic metastasis of bladder cancer." (PMID 40723250, 2025).
ischemic stroke (4 papers, 2021 to 2026). A stroke disorder caused by obstruction of blood flow to the brain, due to thrombotic (local blood clot formation) or embolic (due to a blood clot or other material traveling from another site) event. "Differentially expressed analysis showed that POLR2F, BRCA1, and TRIM21 in this RBPS were associated with ischemic stroke." (PMID 36118697, 2022). "Collectively, our findings identify TRIM21 as a novel astrocyte-specific mediator of neuroinflammation in cerebral ischemic injury and highlight its potential as a therapeutic target for ischemic stroke." (PMID 41852809, 2026).
lymph node metastasis (4 papers, 2023 to 2025). "The results of the univariate Cox regression analysis indicated that TRIM21 expression, tumor differentiation, lymph node metastasis, distant metastasis, and TNM stage were significant prognostic factors for both OS and DSS in CRC patients." (PMID 39890802, 2025). "We found that high TRIM21 expression predicted significant impact on clinical characteristics like decreased lymph node metastasis (RR = 1.12; 95% CI: 0.97–1.30; P < .001), tumor stage (RR = 1.06; 95% CI: 0.82–1.37; P < .001) and tumor grade (RR = 1.07; 95% CI: 0.56–2.05; P < .001)." (PMID 37335642, 2023).
osteoporosis (4 papers, 2023 to 2025). A condition of reduced bone mass, with decreased cortical thickness and a decrease in the number and size of the trabeculae of cancellous bone (but normal chemical composition), resulting in increased fracture incidence. "In conclusion, our results found that Trim21 is elevated in osteoporosis patients and that its deficiency leads to high bone mass compared with that of control littermates in sham-operated and OVX-induced mice." (PMID 37884520, 2023). "Our study provides new evidence that Trim21 is a promising dual-targeting candidate for preventing bone loss and reducing fracture risk in osteoporosis patients." (PMID 37884520, 2023). "Our study highlights the potential therapeutic use of Trim21 as a promising dual-targeting candidate for preventing bone loss and reducing fracture risk in osteoporosis patients." (PMID 37884520, 2023). "Our current study demonstrated that Trim21 is crucial for regulating OB-mediated bone formation and OC-mediated bone resorption, thereby providing a basis for exploring Trim21 as a novel dual-targeting approach for treating osteoporosis and pathological bone loss." (PMID 37884520, 2023). "A similar study demonstrated that TRIM21 expression is significantly increased in bone tissue of osteoporosis patients." (PMID 39563244, 2024). "Collectively, these results highlight the promising role of Trim21 in dual-targeting of OBs and OCs for the treatment of skeletal degenerative disorders, including osteoporosis." (PMID 37884520, 2023). "First, human and mouse bone specimens were evaluated, and the results showed that Trim21 expression was significantly elevated in bone tissues obtained from osteoporosis patients." (PMID 37884520, 2023). "In this study, we first found that the expression of Trim21 was elevated in bone specimens from osteoporosis patients and ovariectomy (OVX)-induced osteoporotic mice." (PMID 37884520, 2023). "In the present study, we demonstrated that Trim21 is crucial for regulating OB-mediated bone formation and OC-mediated bone resorption, thereby providing a basis for exploring Trim21 as a novel dual-targeting approach for treating pathological skeletal diseases, including osteoporosis." (PMID 37884520, 2023). "Notably, we found that Trim21 mRNA levels were increased in patients with osteoporosis (right femur (RF)-BMD T score ≤ −2.5) and osteopenia (RF-BMD T score ≤ −1.0 and > −2.5) compared with those with normal BMDs (T score > −1.0)." (PMID 37884520, 2023). "For further elucidation of the role of Trim21 in osteoanabolic function in pathological bone loss, Trim21+/+ and Trim21−/− mice were sham-operated or underwent an OVX at 12 weeks of age to mimic estrogen deficiency-induced osteoporosis, followed by histological and micro-CT analysis 8 weeks later." (PMID 37884520, 2023). "However, how Trim21 contributes to skeletal degenerative disorders, including osteoporosis, remains unknown." (PMID 37884520, 2023).
prostate carcinoma (4 papers, 2020 to 2025). A carcinoma that arises from epithelial cells of the prostate gland. "We have previously identified TRIM21 as a potential interacting partner of PRMT5 by mass spectrometry in prostate cancer cells." (PMID 32023548, 2020). "Our previous mass spectrometry identified several E3 ligases include CHIP and TRIM21 as interacting proteins of PRMT5 in prostate cancer cells." (PMID 32023548, 2020). "Similar to our findings in the isogenic mES cell lines, we observed significantly higher levels of total G6PD protein and lower levels of Trim21 mRNA in the Pten null T-ALL and prostate cancer models compared with their WT littermates." (PMID 32312982, 2020). "The TRIM21 mRNA and protein levels were upregulated when the WT PTEN, but not the phosphatase-dead CS PTEN, was re-expressed in the PTEN null prostate cancer PC3 cells, accompanied by decreased G6PD levels." (PMID 32312982, 2020).
steatosis (4 papers, 2023 to 2025). Increased lipid within the cytoplasm of cells. "Negative regulation of PEPCK1 and FASN by TRIM21 reduces sustained gluconeogenesis and inhibits steatosis in hepatocytes, thereby significantly alleviating insulin resistance and glucose intolerance." (PMID 37249651, 2023). "In this study, TRIM21 was markedly downregulated in the livers of steatosis patients and obese diabetic mice." (PMID 37249651, 2023). "TRIM21-mediated degradation of these lipogenic activators improved steatosis and hyperglycemia as well as fructose and glucose tolerance." (PMID 37937648, 2023). "Despite the several common phenotypic and biochemical outputs of hepatic TRIM21 overexpression and A1CF silencing, we noticed that the improvement in steatosis was more profound in Ad-Trim21 mice compared with GalNAc-siA1cf–treated mice." (PMID 37937648, 2023). "As shown by immunohistochemistry (IHC) staining, TRIM21 expression in steatosis patients' livers was significantly lower than in non-steatosis livers." (PMID 37249651, 2023). "To confirm the potentially protective role of TRIM21 in the pathogenesis of steatosis and related metabolic disorders, we used an adenoviral approach to achieve TRIM21 overexpression in mouse liver in vivo." (PMID 37249651, 2023). "In contrast to Trim21 overexpression, silencing of Trim21 resulted in increased liver weight and steatosis, as evaluated by liver triacylglyceride measurements and Oil Red O staining." (PMID 37937648, 2023). "Hepatic TRIM21 protects from fructose-induced steatosis via degradation of A1CF." (PMID 37937648, 2023). "Hepatic TRIM21 is markedly reduced in steatosis patients and obese diabetic mice." (PMID 37249651, 2023). "TRIM21 improves steatosis in NASH through inhibition of fructose and lipid metabolism." (PMID 37937648, 2023). "Although the Trim21-overexpression data suggest a TRIM21-mediated ubiquitination-dependent degradation control of ChREBP, it is likely that the transient and incomplete Trim21 silencing we used in this study is inefficient to regulate ChREBP expression and contribute to the exaggerated steatosis." (PMID 37937648, 2023). "Furthermore, we measured increased protein levels of SREBP1, FASN, and ACC upon Trim21 silencing, consistent with the observed enhanced steatosis." (PMID 37937648, 2023). "Furthermore, we measured TRIM21 expression in the livers of patients with steatosis." (PMID 37249651, 2023). "Thus, enhancing this natural counteracting force of steatosis through inhibition of key lipogenic activators via TRIM21-mediated ubiquitination may provide a therapeutic opportunity to treat NASH." (PMID 37937648, 2023). "Similarly, overexpression of TRIM21 inhibits steatosis in vitro." (PMID 37249651, 2023). "The roles of manipulating hepatocyte TGR5 and TRIM21, as well as overexpressing BBOX1 and other therapeutic targets, in the progression from steatosis to MASH were explored in this study, considering both “therapeutic” and “prevention” approaches." (PMID 40344326, 2025). "We further demonstrated in vivo that hepatocyte-specific overexpression of TRIM21 attenuated steatosis in mice fed with a HFru or NASH diet, while conversely, TRIM21 silencing markedly exacerbated it." (PMID 37937648, 2023). "Expression profiling in livers of mice with developing steatohepatitis revealed that, at the time when livers start to accumulate lipids and develop steatosis (12 weeks of NASH diet), A1CF and KHK are induced, while TRIM21 expression starts to increase." (PMID 37937648, 2023). "In this study, we report an upstream mechanism of KHK-C regulation through TRIM21-mediated A1CF ubiquitination and degradation that inhibits KHK-C and establishes a protective mechanism suppressing fructose-induced steatosis." (PMID 37937648, 2023). "In this study, we have identified TRIM21 E3 ubiquitin ligase as a crucial suppressor of DNL- and fructose-mediated steatosis in the liver." (PMID 37937648, 2023).
steatosis (continued). "Previous clinical trials have demonstrated how TRIM21 reduces de novo lipogenesis and steatosis in hepatocytes by inhibiting FASN; this mechanism is detected in patients with TRIM21, which reduces hepatic de novo lipogenesis and steatosis in patients with obesity and MAFLD and obesity." (PMID 39199424, 2024). "Interestingly, we found that protein levels of SREBP1 and ChREBP, 2 transcription factors that play critical roles in hepatic FA synthesis and steatosis, as well as FASN and ACC, 2 rate-limiting metabolic enzymes of DNL, were reduced in TRIM21-overexpressing livers compared with controls." (PMID 37937648, 2023).
cardiac hypertrophy (3 papers, 2024 to 2025). "We also revealed that cardiomyocyte-derived USP28 negatively regulates antioxidant responses and promotes cardiac hypertrophy by deubiquitinating Tripartite Motif Containing 21 (TRIM21)." (PMID 40561034, 2025). "Collectively, we showed that cardiomyocyte USP28 deubiquitinates and stabilizes TRIM21 to negatively regulate antioxidant response, increasing oxidative stress in cardiomyocytes and promoting cardiac hypertrophy and dysfunction." (PMID 39431010, 2024). "Cardiomyocyte USP28 deubiquitinates and stabilizes TRIM21 to negatively regulate nuclear factor erythroid 2-related factor 2 (Nrf2) antioxidant response, increasing oxidative stress in cardiomyocytes and promoting cardiac hypertrophy and injury." (PMID 39431010, 2024). "Therefore, we speculated that USP28 may use TRIM21 as the crucial substrate in regulating cardiac hypertrophy." (PMID 39431010, 2024). "Therefore, we present that USP28 may be a more cardiomyocyte-specific and druggable therapeutic target than TRIM21 for cardiac hypertrophy." (PMID 39431010, 2024). "We then examined whether TRIM21 was required for the regulation of USP28 on antioxidant responses and cardiac hypertrophy." (PMID 39431010, 2024).
dyslipidemia (3 papers, 2023 to 2024). "It is further demonstrated that hepatic overexpression of TRIM21 significantly ameliorates glucose intolerance, insulin resistance, hepatic steatosis, and dyslipidemia in obese diabetic mice." (PMID 37249651, 2023). "Overall, overexpression of hepatic TRIM21 attenuated lipid accumulation and dyslipidemia in obese diabetic mice." (PMID 37249651, 2023). "Next, we assessed the effect of TRIM21 in the development of hepatic steatosis and dyslipidemia." (PMID 37249651, 2023). "Moreover, we showed that TRIM21 overexpression ameliorated glucose intolerance, insulin resistance, hepatic steatosis, and dyslipidemia in obese diabetic mice, whereas its knockdown promoted glucose intolerance, insulin resistance, and triglyceride accumulation." (PMID 37249651, 2023).
heart failure (3 papers, 2022 to 2025). Inability of the heart to pump blood at an adequate rate to meet tissue metabolic requirements. "Kai Hou and colleagues studied the effects of TRIM21 in TRIM21 knockout mice in a doxorubicin treatment model and a left anterior descending branch (LAD)-induced cardiotoxicity model and found that TRIM21 knockout mice were protected from heart failure and death in both models." (PMID 36824370, 2023). "Tripartite motif-containing protein 21 (TRIM21), a member of E3 ubiquitin ligases, is emerging as a mediator in cardiac injury and heart failure." (PMID 36439111, 2022).
Hyperglycemia (3 papers, 2023). An increased concentration of glucose in the blood. "Notably, hepatic TRIM21 overexpression in diet-induced and gene-induced diabetic mice attenuates hyperglycemia and hyperlipidemia." (PMID 37249651, 2023). "Herein, we unexpectedly found that the E3 ligase TRIM21 interacted with and polyubiquitinated the transcription factor FOXD1 to control its protein stability under hyperglycaemic conditions, leading to hyperglycaemia-induced downregulation of FOXD1." (PMID 38092733, 2023). "Interestingly, these changes in TRIM21 expression were independent of hyperglycaemia-induced oxidative stress." (PMID 38092733, 2023).
melanoma (3 papers, 2016 to 2025). A malignant, usually aggressive tumor composed of atypical, neoplastic melanocytes. "Moreover, the rest of SASP-related genes recruited in our risk-scoring model including HLA-B, TPMT, ATM, CD59, TRIM21, and ASPRV1 have not been well studied in melanoma, indicating their potential of novel therapeutic target." (PMID 40864319, 2025).
triple-negative breast carcinoma (3 papers, 2023 to 2024). An invasive breast carcinoma which is negative for expression of estrogen receptor (ER), progesterone receptor (PR), and human epidermal growth factor receptor 2 (HER2). "Low TRIM21 expression is correlated with poor overall survival in triple-negative breast cancer patients, and knockout of TRIM21 promotes the proliferation, migration, and invasion capability of triple negative breast cancer (TNBC) cells." (PMID 38225560, 2024). "By disrupting the TGF-β signaling pathway, TRIM21/Ro52 can suppress triple-negative breast cancer cell metastasis." (PMID 37993883, 2023).
acute myeloid leukemia (2 papers, 2022 to 2024). Acute myeloid leukemia (AML) is a group of neoplasms arising from precursor cells committed to the myeloid cell-line differentiation. "TRIM21 mediates the degradation of the autophagic lysosomal pathway of cyclin-dependent kinase 2 (CDK2) to inhibit the proliferation of acute myeloid leukemia." (PMID 39154024, 2024).
AIDS (2 papers, 2018 to 2022). A syndrome resulting from the acquired deficiency of cellular immunity caused by the human immunodeficiency virus (HIV). "TRIM21 is anticipated to boost the potency of antibodies targeting intra-cellular proteins in HIV/AIDS treatment, however, further investigations are warranted." (PMID 29415435, 2018).
breast tumors (2 papers, 2023 to 2024). "In addition to the decreased expression of TRIM21 in colorectal and breast tumors, the alteration of TRIM21 expression was also observed in some other types of tumors." (PMID 36749630, 2023).
calcinosis (2 papers, 2016 to 2023). Deposition of calcium in the tissues. "Interestingly, the majority of subjects who had ILD had either ATA or anti-Ro52/TRIM21 overlapping antibodies, whereas most subjects with calcinosis had ACA overlapping antibodies." (PMID 27583908, 2016).
colorectal tumor (2 papers, 2018 to 2023). "Meanwhile, we verified the influence of TRIM21 on the ferroptosis sensitivity of SW480 cells for colorectal tumor, SGC‐7901 cells for stomach tumor, and HuCC‐T1 cells for cholangiocarcinoma." (PMID 37587773, 2023).
Erythema (2 papers, 2021 to 2024). Redness of the skin, caused by hyperemia of the capillaries in the lower layers of the skin. "The cluster 1 of patients, which had a moderate risk of infection, had a high probability of positive mechanic’s hands, periungual erythema, anti-TRIM21 antibody, and anti-Jo1 antibody." (PMID 39165359, 2024).
fatty liver (2 papers, 2023). "Together, the results from Trim21-knockdown experiments further strengthen the notion that TRIM21 activation during chronic inflammatory and metabolic stress dampens metabolic pathways, leading to the development of hepatic steatosis." (PMID 37937648, 2023). "Our study identifies TRIM21 as a negative regulator of liver steatosis in NASH and provides mechanistic insights into an immunometabolic crosstalk that limits fatty acid synthesis and fructose metabolism during metabolic stress." (PMID 37937648, 2023). "Importantly, in liver biopsies of patients without fatty liver disease (FLD) and with NASH, TRIM21 expression was markedly induced in steatohepatitis." (PMID 37937648, 2023).
gallbladder cancer (2 papers, 2025). "Given that TAT as a pro-metastasis regulator, TRIM21 may exert inhibitory effects on liver metastasis of gallbladder cancer." (PMID 40735642, 2025).
inflammatory bowel disease (2 papers, 2019 to 2022). A spectrum of small and large bowel inflammatory diseases of unknown etiology. "Previous studies showed that genetic ablation of TRIM21 in mice conferred protection from Lipopolysaccharide (LPS)-induced inflammation and dextran sulfate sodium (DSS)-induced inflammatory bowel diseases (IBD) model." (PMID 36159815, 2022). "TRIM21 also influences T cell differentiation by targeting IRF3 to inhibit ex vivo Th1 and Th17 differentiation in CD4+ T cells isolated from inflammatory bowel disease (IBD) patients." (PMID 30741923, 2019).
kidney cancer (2 papers, 2020 to 2025). Primary or metastatic malignant neoplasm involving the kidney. "The expression levels of TRIM14, PML, and TRIM21 were significantly higher in kidney cancer tissues than in normal tissues." (PMID 33173411, 2020).
kidney clear cell carcinoma (2 papers, 2023 to 2025). "In renal clear cell carcinoma, Trim21 acts as an E3 ubiquitin ligase for HIF-1α, promoting its ubiquitination and degradation, thereby inhibiting glycolysis and suppressing the growth and metastasis of renal clear cell carcinoma." (PMID 41298345, 2025).